APOE (apolipoprotein E)
Diseases named in the same sentence as APOE in open-access papers (continued):
Sharing a sentence is not in itself a finding about the gene and the disease.
dementia (continued). "In our study, though, the presence of the APOE ε4 status has a non-significant contribution in predicting the conversion to dementia in MCI patients when considering the AT(N) profile, which acts as a proxy of AD pathology." (PMID 36674881, 2023). "In addition to A− and T-status, age, sex, APOE ε4-status and stage of cognitive impairment (CU, MCI or dementia) were included as covariates." (PMID 37221606, 2023). "The pattern of results for amyloid status attenuated with exclusion of those with dementia and MCI (n = 10, [-0.06, p=0.02] to [-0.03 p = 0.1]), but otherwise effect sizes remained similar after adjusting for APOE-ε4 and affective mental health problems at the time of cognitive assessment (A.5)." (PMID 36470133, 2023). "A study including 198,965 dementia-free participants aged ≥60 used a PRS based on 38 non-apolipoprotein E single-nucleotide polymorphisms and APOE ε4 status to determine the genetic risk for dementia." (PMID 36983321, 2023). "The important features of this dataset were Mini-Mental State Exam (MMSE), age, Judgment, memory, APOE (apolipoprotein E gene), Personal care, height, weight, Orient (recent and long-term memory testing), Clinical Dementia Rating (CDR), and Sumbox (clinical dementia rating scale)." (PMID 37972072, 2023). "The CLU rs11136000 C allele predicts increased ventricular expansion in the brain, regardless of dementia status or APOE genotype." (PMID 37047762, 2023). "Higher plasma ApoA1 in dementia APOE ε4 non-carriers also related to faster decline in LM scores (β − 2.75 [95% CI, − 4.27 to − 1.24], p < 0.001)." (PMID 36927447, 2023). "In ADSP participants without dementia, ADNC was lower in CHIP carriers compared to noncarriers with the APOE ε3ε3 genotype or with an APOE ε4 allele, but this effect was seen not in those with APOE ε2ε2 or APOE ε2ε3 genotypes." (PMID 37322115, 2023). "Recently, a large-scale examination of AD and related dementias (ADRD), APOE ε4, posttraumatic stress disorder (PTSD), and traumatic brain injury (TBI) in US veterans from the Million Veteran Program (MVP) observed that ε4, PTSD, and TBI were all major ADRD risk factors." (PMID 37629231, 2023). "Previous studies have employed two main operationalisations of cognitive resilience in APOE ɛ4 positive adults (i.e. absence of dementia or cognitive performance/trajectory)." (PMID 37198167, 2023). "For non-carriers of APOE ε4, higher PRS 1–3 significantly increased the hazard of all-cause dementia and all PRS increased the hazard of vascular dementia (average HR per SD of PRS 1.2, P < 0.002)." (PMID 37091584, 2023). "For dementia, we found the PRS (excluding APOE) in Black participants is lower than in Whites." (PMID 37124771, 2023). "Fourthly, although the multivariate analysis was used to adjust factors such as age, gender, smoking, drinking, years of education, APOE, physics activity, cognitive activity, BMI, and CESD, the impact of other confounders on the incidence of dementia cannot be completely excluded." (PMID 36505244, 2022). "Moreover, we found higher T-tau and P-tau levels with some SVD markers in APOE ε4/4 carriers in patients with MCI, reflecting the importance of SVD markers in an early stage of dementia, possibly contributing to the dementia pathophysiology." (PMID 35912087, 2022). "Not only the APP gene is responsible for dementia in DS, GATD3A, SOD1, ERG, BACE2, DSCR1/RCAN1, APOE (19q13.32), BACE1 (11q23.3), IL1B (2q14.1), GSAP (7q11.23), UBB (17p11.2), and IRS1 (2q36.3) genes may also play a major role in dementia in DS." (PMID 35676933, 2022). "Two-way interactions were examined for each of the three transitions and only sex × amyloid and sex × APOE for the without dementia to dementia transition were significant." (PMID 35310829, 2022). "Nonetheless, neither the total CSF apoE concentration nor its isoforms were related to Aβ status nor the degree of dementia of the AD patients, in agreement with prior studies." (PMID 36153580, 2022).
dementia (continued). "Within each amyloid group, the hazard of incident dementia was higher for APOE ɛ4 carriers than non-carriers for women (HR 2.24, 95% CI 1.80–2.77) and men (HR 1.37, 95% CI 1.09–1.71)." (PMID 35310829, 2022). "Patients’ GBA status did not predict progression to dementia though their APOE ε4 status did (Univariate HR2.08, 95% CI 1.16 to 3.73, p=0.014, Multivariate HR 3.12, 95% CI 1.63 to 6.00, p=0.001)." (PMID 35577512, 2022). "Interaction terms with cost-to-capacity × subsequent normal/MCI/dementia status and cost-to-capacity × APOE status were not significant at the FDR-adjusted level (p < 0.01) and removed from the final models." (PMID 35440799, 2022). "In a population with pre‐existing occlusive vascular disease or at high vascular risk, after allowing for age, weight loss was the strongest predictor of the incidence of recorded dementia in the absence of a cognitive function measure and APOE genotype." (PMID 36092692, 2022). "Compared to individuals without incident dementia, individuals with incident dementia tended to be older, male, APOE ε4 carriers, and smokers; were more likely to take cholesterol-lowering medications, and insulin." (PMID 35927253, 2022). "Obesity led to reductions in myelin/neurite packing and size/complexity regardless of APOE and family history of dementia status." (PMID 35303671, 2022). "In a stepwise selection model for predictors of dementia (with standard adjustment) when cognitive function and APOE genotype were not made available, weight change was selected first." (PMID 36092692, 2022). "Lower RSFC in the DMN and DAN was linked to peripheral pro-inflammatory signaling in older adults without dementia, and was further magnified in APOE ε4 carriers." (PMID 36533177, 2022). "In models not adjusting for APOE 4 status, the magnitude and direction of RHR’s associations with dementia are sustained." (PMID 36199126, 2022). "Theoretical effects on years of life free of AD and all-cause dementia per a Q5 to Q1 difference in RBC DHA were compared with the estimated effects of age (per 1 year older at baseline) and APOE-ε4 (compared with non-carriers)." (PMID 35745137, 2022). "The OR of the brain age residual for MCI and dementia was not affected by demographic factors, APOE e4 status, or amyloid deposition status." (PMID 35974140, 2022). "Compared with the nondementia group, the number of APOE-ε4 gene carriers in the dementia group was significantly increased (P < 0.05)." (PMID 35317127, 2022). "Another study also evaluated epigenetic age acceleration in incidental dementia, and adjusted for multiple covariates including APOE genotype, age, and sex, but did not observe a relationship between age acceleration and dementia incidence." (PMID 36389222, 2022). "We did not have access to the participants’ APOE e4 status, but we did not analyze dementia subtypes either." (PMID 35783131, 2022). "In conclusion, we demonstrate superior performance of the LC-MS platform over Simoa assays for plasma amyloid-β and p-tau181, and over a model incorporating age, sex and APOE ε4 carrier status, in screening for concurrent PET amyloid status in a large number of dementia-free individuals." (PMID 33479777, 2021). "Understanding the interplay of cardiometabolic riskfactors and apolipoprotein E (APOE) may direct us to a more personalizedmedicine and preventative care in MCI and dementia." (PMID 33907599, 2021). "In the CSF of middle-aged adults (average age 54.5 years) with no dementia, apoE particles were smaller in both ε3/ε4 and ε4/ε4 individuals than in ε3/ε3 individuals, but larger in ε2/ε3 individuals." (PMID 33679311, 2021). "Probability of conversion to dementia in the subsample was 1.7 times more frequent between APOE-Ɛ4 carriers than in non-carriers (χ2 = 15.4, p < .001), but the distribution of APOE-Ɛ4 carriers was homogeneous between the 4 class groups (χ2 = .14, p = .99)." (PMID 33742011, 2021).
dementia (continued). "In contrast, our Dementia-only GWAS study did not support an APOE locus involvement in SARS-CoV-2 pathobiology or COVID-19 prognosis." (PMID 34945790, 2021). "Our results are further consistent with prior research indicating that the greatest driver for age of onset of dementia in Black individuals is not APOE, as onset of dementia is earlier in Blacks regardless of ε4 status." (PMID 34744974, 2021). "Within the Cardiovascular Risk Factors, Aging, and Incidence of Dementia (CAIDE) study, the late-life risk of dementia was reported to increase in ApoE-ε4 carriers with an unfavorable (non-genetic) risk profile at midlife." (PMID 34764935, 2021). "The effect of ApoE-ε4 is thought to attenuate with increasing age and dementia onset in ApoE-ε4 carriers occurs at an earlier age compared to non-carriers." (PMID 34764935, 2021). "Among White males, 40.6% (95% CI: 37.0, 44.3%) and 27% (95% CI: 24.5, 29.1%) of APOE ε4 carriers and non-carriers, respectively, developed dementia (p < 0.01)." (PMID 34744974, 2021). "Carriers of the apolipoprotein (APOE) ε4 allele contribute to 7% of incident global dementia cases and have double the risk of developing mild cognitive impairment (MCI) and dementia than have non-carriers." (PMID 34744974, 2021). "The selection of ApoE and 5-HTTLPR genotypes to test the hypothesis of GxE interactions was based on the strong social impacts on mental health, including dementia and depression." (PMID 34647905, 2021). "Of non-APOE-ε4 carriers, 0.89% (95% CI 0.73–1.08%) current smokers developed dementia compared with 0.49% (95% CI 0.44–0.55%) of never smokers (adjusted HR 1.78; 95% CI 1.39–2.29)." (PMID 34155245, 2021). "A further limitation is that we were not able to completely rule out the role of AD/dementia, in particular preclinical dementia, in cognitive decline observed in APOE ε4 carriers." (PMID 33397450, 2021). "The median age at dementia diagnosis for White females was 83.4 years (95% CI: 82.8, 84.0) in APOE ε4 carriers and 86.4 years (95% CI: 85.9, 86.9) in non-carriers." (PMID 34744974, 2021). "Notably, the association of PRS with progression risk was stronger in APOE ε4 non-carriers than in APOE ε4 carriers in MCI, showing a significant interaction between PRS+APOE and APOE ε4 carrier status on the conversion of MCI to dementia." (PMID 34465370, 2021). "Black participants overall had an earlier age of dementia diagnosis or ascertainment and an earlier age of dementia-free death than had White participants, regardless of APOE status." (PMID 34744974, 2021). "However, there was an interaction between APOE ɛ4 carriership and the 39‐SNPs AD‐PRS (P = .02), and between APOE ɛ4 status and the 1e–5 AD‐PRS (P = .05) in relation to incident dementia." (PMID 33532541, 2021). "To further elucidate the influence of APOE and MAPT variability on dementia in Parkinson's disease, we genotyped postmortem brain tissue samples of clinically and pathologically well-characterized Parkinson's donors and performed a survival analysis of time to dementia." (PMID 33613437, 2021). "APOE ε4 was associated with cognitive decline, but PRS was not, suggesting that APOE genotype has a stronger effect than PRS on both dementia and cognitive decline." (PMID 34041846, 2021). "Adding apolipoprotein E (APOE) ε4 as a covariate in the analysis did not alter observed associations between sleep duration at age 50, 60, and 70 and risk of dementia." (PMID 33879784, 2021). "We also found that the effect of the PGS on dementia was not significantly different by APOE status." (PMID 33143703, 2020). "In our longitudinal data, APOE e4 carrier showed a steeper incline slope in a clinical dementia rating sum of boxes (CDR-SB) score than APOE e4 non-carrier in SMI (B = 0.0066, p = 0.0104), E-aMCI (B = 0.0313, p < 0.0001), and L-aMCI (B = 0.0178, p = 0.0007)." (PMID 32770103, 2020).
dementia (continued). "APOE did not affect the association of LPA C16:0 and C16:1 to MCI to AD dementia progression while the association was lost upon adjusting for Aβ-42 levels." (PMID 33008436, 2020). "Our finding that T3 may have a protective effect on memory in APOE ε4 carriers with SCD has clinical significance in terms of prevention of cognitive deterioration and dementia." (PMID 32671080, 2020). "The role of DNA methylation of the genomic region of apolipoprotein E (APOE) and its association to CF in individuals without dementia was studied in older African Americans from the Genetic Epidemiology Network of Arteriopathy." (PMID 32457596, 2020). "Aside from its established role in AD, not much is known about how APOE influences disease pathogenesis in AD related dementias such as Fronto-temporal dementias (FTD), dementia with Lewy bodies (DLB) and vascular dementia." (PMID 32005122, 2020). "With regard to apoE subspecies, in the absence of apoC3, higher apoE in the HDL fraction of plasma was associated with better cognitive function and a lower risk of dementia and AD." (PMID 32648923, 2020). "Including the APOE region in PGS without specific measurement of APOE-ε4 is insufficient, and overestimates the polygenic nature of dementia." (PMID 33143703, 2020). "First, information on other potential influencing factors (e.g., the level of apolipoprotein E, lifestyle, education, and family history of dementia) was not available on the NHIRD." (PMID 33253311, 2020). "APOE e4 carrier showed a steeper incline slope in a clinical dementia rating sum of boxes (CDR-SB) score than APOE e4 non-carriers in SMI (B = 0.0066, p = 0.0104), E-aMCI (B = 0.0313, p < 0.0001), and L-aMCI (B = 0.0178, p = 0.0007)." (PMID 32770103, 2020). "APOE ɛ4 and long work duration seem to enhance the impact of such negative work scenario on dementia occurrence." (PMID 32081835, 2020). "However, in addition to the described metabolic relationship between APOE, HDL, and AD, brain neuroinflammation is a fundamental connection point between dyslipidemia and dementia." (PMID 33126696, 2020). "In this study, higher apoE levels in HDL lacking apoC3 in an older population were associated with better cognitive function and a lower risk of dementia or AD." (PMID 32648923, 2020). "For each person, APOE genotype, PlsEtn Biosynthesis value (PBV, the combination of three key PlsEtn species), cognition (the combination of five specific cognitive domains), and diagnosis of dementia was determined." (PMID 31022959, 2019). "In the context of neurodegenerative diseases, and dementia in particular, extensive analyses have shown that APOE genotype influences cognitive and non-cognitive phenotypes of subjects with a clinical diagnosis of MCI or AD (clinically probable AD)." (PMID 30677746, 2019). "APOE genotypes were typical of a population with dementia: 11/14 Alzheimer’s cases and one of the four non-Alzheimer’s cases with known APOE genotypes were APOE ɛ4 carriers." (PMID 31157360, 2019). "At baseline there was a statistically significant difference in IGF-I receptor stimulating activity between ApoE-ε4 genotype groups without dementia (non-carrier, heterozygote and homozygote), after adjustment for age and sex (p = 0.04)." (PMID 30809143, 2019). "MCI patients classified as “neurochemically probable AD” had 8–12 times higher hazards to develop dementia than those classified as “neurochemically improbable AD”, adjusted for age, gender, MMSE score, and APOE genotype, and these hazard ratios were apparently time independent." (PMID 30611311, 2019). "The probability of dementia in participants with either a high PBV or an APOE ε2ε3 genotype was indistinguishable." (PMID 31022959, 2019). "Additional predictors included poorer cognition, APOE ε4 genotype, higher systolic blood pressure, and lower body mass index, but not the CAIDE dementia risk score." (PMID 31805990, 2019).
dementia (continued). "Here we did not observe any effects of APOE genotype or of family history of dementia on obesity status for the whole group, and APOE genotype did not have any mediating effects on the observed WHR-fornix MPF correlation in men (p = 0.68)." (PMID 30735826, 2019). "It has been speculated that the association between hyperlipidemia and dementia is affected by several factors, such as apolipoprotein E (APOE) ε4 and the type of dementia." (PMID 30856540, 2019). "TBI is a potential risk factor only for subsequent dementia, TDP-43, and FTD, but not for AD, PD, or APOE-associated neurodegeneration." (PMID 30396335, 2018). "Most prior studies examining the etiology of dementia have focused on factors that are negative (e.g., smoking) or immutable (e.g., race) or both (e.g., APOE ε4)." (PMID 29414991, 2018). "Among those with APOE ε4, those with positive age beliefs were 49.8% less likely to develop dementia than those with negative age beliefs." (PMID 29414991, 2018). "In this study, the analysis of two MRI modalities, ASL and DTI, revealed that ACS protects against the putative detrimental effect of APOE e4 molecules on brain aging in healthy volunteers without dementia." (PMID 29896423, 2018). "However, HIV-infected Apoε4 carriers had higher CSF ApoE levels, comparable to those of the SN controls, and the higher levels correlated with lower cognitive performance (HIV Dementia Scale and Global Cognitive Score)." (PMID 29987582, 2018). "That is, the dementia conversion rate of those with APOE ε4 was 4.50%; whereas, it was 2.36% for those without APOE ε4." (PMID 29414991, 2018). "Apolipoprotein E (APOE) genotype is believed to play a role in the onset of dementia, though less is known about its relationship with non-pathogenic age-related cognitive decline." (PMID 30339707, 2018). "While we did not estimate lifetime cumulative incidence for NACC given the short mean duration of follow-up, it would be expected to be considerably higher than the 5-y estimates—in the oldest APOE-e4/e4 homozygote individuals, 38.3% for MCI or dementia and 12.4% for dementia alone." (PMID 28323826, 2017). "For dementia patients, sVEGFR2 levels were 7% lower in ApoE ε4 carriers than in non-carriers, but the difference was not significant (p = 0.073)." (PMID 29255164, 2017). "Other studies, however, suggest that physical activity is related to a lower incidence of dementia and higher level of cognitive functioning in APOE ε4 non-carriers." (PMID 28327083, 2017). "More APOE ε4-positive participants had dementia (65%) than APOEε4 negative participants (40%), consistent with the role of this gene as a primary genetic risk factor for AD." (PMID 29120328, 2017). "Apolipoprotein E has been studied as a potential biomarker previously in dementia but due to only small changes or ambiguity between studies, the levels of apolipoprotein E have not been considered diagnostically useful." (PMID 26627638, 2015). "To conclude, the current results suggest that lower white matter integrity represents one possible mechanism through which APOE affects PS performance in elderly persons without dementia." (PMID 26252210, 2015). "A single-phase survey (baseline) of all over 65-year-olds residing in sevencatchment areas in Cuba (n=2944) was conducted between 2003 and 2007.Dementia diagnosis was established according to DSM-IV and 10/66 criteria.APOE genotype was determined in 2520 participants." (PMID 29213926, 2014). "The transition probabilities from moderate to severe dementia as measured by CDRGLOB range from 4.3% (Age = 55, no APOE-4 allele) to 31.1% (Age = 85, two APOE-4 alleles)." (PMID 24073268, 2013). "The analysis included 4,830 subjects who did not have dementia at baseline, and for whom information was available on ApoE genotype, ACE inhibitor use, and the follow-up diagnoses on AD." (PMID 23948883, 2013).